COL23A1 (collagen type XXIII alpha 1 chain)
Synonyms: DKFZp434K0621
Tractability: Antibody: its Gene Ontology location is reachable by antibodies, with high confidence; UniProt places it where antibodies can reach, with medium confidence; UniProt predicts a signal peptide or a membrane-spanning region. PROTAC: ubiquitination databases record sites on it.
Gene: Protein-coding gene on chromosome 5 (178,237,476 to 178,590,393, reverse strand). Ensembl gene ENSG00000050767.
Subcellular location: Cell membrane
Pathways (Reactome):
Extracellular matrix organization: Collagen biosynthesis and modifying enzymes; Collagen chain trimerization; Collagen degradation; Integrin cell surface interactions
Gene Ontology:
Molecular function: protein binding; extracellular matrix structural constituent conferring tensile strength; heparin binding; identical protein binding
Biological process: extracellular matrix organization
Cellular component: extracellular matrix; collagen type XXIII trimer; endoplasmic reticulum lumen; plasma membrane; cell surface; extracellular region
Genetic constraint (gnomAD): Loss-of-function variants: 90 observed, 80.99 expected, observed/expected ratio (o/e) 1.11, 90% interval 0.94 to 1.32. The synonymous counts are far from expectation, so gnomAD's model fits this gene poorly and the ratio says little. Missense variants: 723 observed, 622.04 expected, observed/expected ratio (o/e) 1.16, 90% interval 1.09 to 1.24. Synonymous variants: 311 observed, 242.56 expected, observed/expected ratio (o/e) 1.28, 90% interval 1.17 to 1.41.
Homologues: Orthologues: rabbit COL23A1 (93% identical), pig COL23A1 (90% identical), dog COL23A1 (90% identical), mouse Col23a1 (89% identical), rat Col23a1 (89% identical), macaque COL23A1 (59% identical), zebrafish col7a1l (40% identical), zebrafish si:dkey-117n7.4 (29% identical). Paralogues in human: COL25A1 (55% identical), COL11A1 (45% identical), COL5A1 (44% identical), COL11A2 (43% identical), COL5A3 (40% identical), COL2A1 (39% identical), COL4A5 (39% identical), COL5A2 (38% identical), COL4A1 (38% identical), COL1A1 (38% identical), COL4A4 (37% identical), COL4A2 (37% identical), and 25 more.
Diseases named in the same sentence as COL23A1 in open-access papers:
COL23A1 is named in the same sentence as 27 diseases in open-access papers, as found by Europe PMC text mining. Sharing a sentence is not in itself a finding about the gene and the disease. The quoted sentences say what the papers report.
clear cell renal cell carcinoma (5 papers, 2017 to 2023). "The COL23A1 gene can be used as a surrogate marker for monitoring disease activity in ulcerative colitis and Crohn’s disease, as well as a biomarker for papillary thyroid cancer and clear cell renal cell carcinoma." (PMID 37144136, 2023).
prostate carcinoma (5 papers, 2009 to 2024). A carcinoma that arises from epithelial cells of the prostate gland. "Collagen Type XXIII Alpha 1 Chain (COL23A1) is reportedly associated with prostate cancer recurrence and distant metastases and clinical stages in thyroid carcinoma." (PMID 38163849, 2024). "Survival analysis showed significant prognostic implications of COL23A1 expression in non-small cell lung cancer and prostate cancer." (PMID 30846004, 2019). "One of the major expression sites of COL23A1 is skin, and its increased expression relates to the recurrence and metastasis of prostate cancer, which implies the existence of extracellular matrix turnover." (PMID 19287495, 2009). "The same study also reported that COL23A1 was upregulated in prostate cancer tissues, and might be an independent predictor of PSA-defined disease recurrence." (PMID 28852123, 2017).
thyroid cancer (3 papers, 2024 to 2026). "Previous research has highlighted collagen genes, such as COL13A1 and COL23A1, as key players in thyroid cancer." (PMID 42306204, 2026).
papillary thyroid cancer (2 papers, 2017 to 2023). "Therefore, we inferred that the aberrant expression of COL23A1 may also affect tumor development in papillary thyroid carcinoma." (PMID 28272462, 2017).
Cirrhosis (1 paper, 2015). A chronic disorder of the liver in which liver tissue becomes scarred and is partially replaced by regenerative nodules and fibrotic tissue resulting in loss of liver function. "Patients with cirrhosis showed increased expression in blood of eight genes coding for collagen synthesis COL4A6, COL5A1, COL11A2, COL12A1, COL27A1, COL28A1, COL23A1, COL14A1." (PMID 26317806, 2015).
dilated cardiomyopathy (1 paper, 2016). Cardiomyopathy which is characterized by dilation and contractile dysfunction of the left and right ventricles. "Upregulated COL4A5, COL9A1, COL21A1, and COL23A1 genes, encode collagens that have not previously been reported to be related to dilated cardiomyopathy." (PMID 27936202, 2016).
Hernia (1 paper, 2009). "Aberrant collagen metabolism has been considered to be the main reason considered for hernia development, and COL23A1 was identified to be associated with hernia development in our study." (PMID 19287495, 2009). "The SNP in COL23A1 (COL23A1-E2) was highly significantly associated with hernias (p<0.001)." (PMID 19287495, 2009). "These genes may be involved in the estrogen receptor signaling pathway (KIF18A and NPTX1), the epithelial-mesenchymal transition (ELF5) and the collagen metabolism pathway (COL23A1), which are associated with the important molecular characteristics of hernia pathophysiology." (PMID 19287495, 2009). "This could also suggest the involvement of COL23A1 in hernia development." (PMID 19287495, 2009).
idiopathic pulmonary fibrosis (1 paper, 2025). Idiopathic pulmonary fibrosis (IPF) is a nonneoplastic pulmonary disease that is characterized by the formation of scar tissue within the lungs in the absence of any known cause. "‘COL23A1+ adventitial fibroblasts’ shared key markers (COL15A1, ENTPD1, PLCL1) with peribronchial fibroblasts, a subpopulation specifically localized around the airway epithelium, which is enriched in idiopathic pulmonary fibrosis and may be implicated as a key cell type in lung disease." (PMID 40114924, 2025).
metastatic prostate carcinoma (1 paper, 2022). A carcinoma that arises from the prostate gland and has spread to other anatomic sites. "COL23A1 is suggested to be highly expressed in metastatic prostate cancer compared with benign prostate tissue." (PMID 36010952, 2022).
rotator cuff tears (1 paper, 2022). "Based on the risk of being damaging and on the potential role in rotator cuff etiopathogenesis, three candidate genes for rotator cuff tears were prioritized: COL23A1, EMILIN3 and HDAC10." (PMID 36358266, 2022).
tumor (6 papers, 2017 to 2026). "Investigations of COL23A1 in many malignancies have implicated an important role in tumor maintenance." (PMID 28852123, 2017). "COL13A1 was significantly upregulated, while COL23A1 was downregulated in tumor tissues compared to normal tissues." (PMID 42306204, 2026). "We found COL23A1 mRNA was elevated in tumor compared with adjacent normal tissues, which was further validated by TCGA cohort." (PMID 28852123, 2017). "There was a significant correlation between high COL23A1 expression and larger tumor size (P = 0.017)." (PMID 28852123, 2017). "For tumor diameter ≤ 4 cm, only 41.7% (43/103) of tumors had high COL23A1 expression; however, this proportion increased to 62.5% (30/48) for tumors larger than 4 cm (P = 0.017)." (PMID 28852123, 2017). "IHC results from 151 ccRCC cases suggested that high COL23A1 expression correlated with larger tumor size (P = 0.017) and advanced T stage (P = 0.011)." (PMID 28852123, 2017). "The mRNA level of COL23A1 was further validated by TCGA database, which showed significantly increased COL23A1 expression in 72 ccRCC tumor tissues than paired ANTs." (PMID 28852123, 2017). "COL23A1 overexpression was correlated with more aggressive tumor behavior." (PMID 28852123, 2017). "Expression levels vary by sample type, tumor stage, and histology, with higher COL13A1 staining intensity and moderate COL23A1 staining observed in tumors." (PMID 42306204, 2026).
infection (1 paper, 2024). The state of being infected such as from the introduction of a foreign agent such as serum, vaccine, antigenic substance or organism. "The presence of a soluble form of COL23A1 may limit the infection of keratinocytes with the HSV-1 herpes virus, while blocking the degradation process and release of COL23A1 into the extracellular matrix (ECM) increases susceptibility to infection by HSV-1." (PMID 39062889, 2024).
musculoskeletal disorders (1 paper, 2022). "Although this protein has not been so far associated with musculoskeletal disorders, the high conservation of identical COL23A1 nucleotide sequences in other collagen genes could suggests a possible role in tissue stability." (PMID 36358266, 2022).
COL23A1 also shares sentences with these, for which no sentence is quoted: cancer (5 papers); ovarian carcinoma (2); cardiovascular disease (1); Crohn disease (1); endometrial cancer (1); hepatocellular carcinoma (1); Inguinal hernia (1); keratoconus (1); lung disease (1); non-small cell lung carcinoma (1); Obesity (1); prostate (1); Stroke (1); ulcerative colitis (1).